LDHA (lactate dehydrogenase A)
Diseases named in the same sentence as LDHA in open-access papers (continued):
Sharing a sentence is not in itself a finding about the gene and the disease.
cancer (continued). "Significantly less cytoplasmic LDHA staining was observed in malignant tumors compared to normal brain tissue, which was equivalent to CANT (50% vs. 89% vs. 76%, respectively p = <0.001)." (PMID 33996536, 2021). "Knockdown of LDHA expression in cancer cells inhibits tumorigenicity through increasing mitochondrial respiration and reducing cell viability." (PMID 34065602, 2021). "LDHA expression is controlled by miR-34a, miR-34c, miR-369-3p, miR-374a, and miR-4524a/b, which are commonly down-regulated in cancer tissues, such as in colorectal cancer." (PMID 34298698, 2021). "Given the central role of LDHA for tumorigenicity, targeting lactate metabolism is a promising approach for cancer therapy." (PMID 32034005, 2020). "LDHA is becoming a promising new target in cancer therapy due to its high expression and correlation to poor prognosis in tumors." (PMID 32859246, 2020). "As LDHA is a vital supporter of glucose metabolism in cancer cells and its increased level is a marker for many tumors, LDHA can be defined as an anticancer drug target." (PMID 32121469, 2020). "In cancer cells, a large fraction of pyruvate is converted into lactate preferentially by LDHA, with NAD+ as a cofactor, even with high oxygen availability (called the Warburg effect), minimizing pyruvate’s entry into the Krebs cycle in the mitochondria." (PMID 33339207, 2020). "Studies have reported for the first time that the overexpression of LDHA is essential for the development of Taxol resistance in cancer cells." (PMID 32038983, 2020). "The results showed that P4HA1 was correlated with PGK1 (r = 0.16~0.81) in 25 cancer types and correlated with LDHA (r = 0.13~0.79) in 24 cancer types (p < 0.05)." (PMID 32635458, 2020). "We analyzed tissue lactate concentration, LDH activity, and isozyme pattern, and LDHA/LDHB protein expression and localization in cancer-associated adipose tissue, compared to the breast adipose tissue of women with benign breast changes." (PMID 33353120, 2020). "While LDHA is upregulated in variety of cancers, LDHB is specifically upregulated in basal-like TNBC and is an essential gene in TNBC." (PMID 32350346, 2020). "Studies in different cancer types have reported that LDHA overexpression stems from mechanisms involving transcriptional, post-transcriptional, and post-translational regulation." (PMID 33324565, 2020). "Among all functional groups of proteins associated with SEMGs, we have focused on two key enzymes of cancer-related metabolism—LDHA and PKM." (PMID 33311447, 2020). "Given the importance of lactate metabolism in different types of cancers, optimizing existing compounds while continuing the search for and development of new LDHA inhibitors would be a reasonable strategy." (PMID 33153193, 2020). "It is clear that cancer cells mainly produce energy through glycolysis and LDHA is the final enzyme involved in this pathway." (PMID 32121469, 2020). "LDHA is commonly upregulated in several rapidly grown tumors, allowing cancer cells to survive and proliferate under hypoxic conditions (0.5% oxygen)." (PMID 33339207, 2020). "ANRIL promotes GLUT1 and lactate dehydrogenase A (LDHA) expression, resulting in the upregulation of glucose uptake and the promotion of cancer progression via the AKT/mTOR pathway." (PMID 32331347, 2020). "Lactate dehydrogenase A, encoded by LDHA, converts pyruvate to lactate and generates ATP—and this pathway has been shown to be an essential source of energy for cancer cells." (PMID 33019722, 2020). "MYC invariably promotes expression of critical enzymes involved in aerobic glycolysis, such as HK2 and LDHA, making cancer cells more vulnerable to glycolysis inhibition." (PMID 32651356, 2020). "Several in vitro studies showed that overexpression of LDHA in cancer cells leads to increased proliferation and invasion as part of the epithelial-mesenchymal transition as well as resistance to apoptosis and protective autophagy in tamoxifen resistance." (PMID 33353120, 2020).
cancer (continued). "LDHA does not only mediate cancer progression, but it can also influence the sensitivity of BC cells to anticancer drugs." (PMID 32806533, 2020). "For example, as tumors grow, oxygen becomes scarce and lactate dehydrogenase A (LDHA) is upregulated as cancer cells shift to aerobic glycolysis generating lactate as a by-product." (PMID 32992762, 2020). "Conversely, in cancer cells, pyruvate is transformed into lactate by lactate dehydrogenase A (LDHA) and the yield of ATP is far lower, as only two ATP molecules are released per molecule of glucose through glycolysis." (PMID 32843908, 2020). "Relative levels of LDHA mRNA expression also significantly differed among the tissues, increasing 1.6-fold in low-grade cancer and 2.5-fold in high-grade cancer compared to benign tissue." (PMID 32110965, 2020). "LDHA (lactate dehydrogenase A), a crucial enzyme of energy metabolism, is elevated in various cancers compared with normal tissues." (PMID 33287749, 2020). "Studies have reported that HIF1-induced LDHA and PDK-1 cause the Warburg effect, which enhances glucose metabolism in cancer cells." (PMID 31936895, 2020). "Galloflavin, another LDHA inhibitor, showed two different mechanisms of inhibition of cancer cell proliferation." (PMID 32806533, 2020). "Consistently, knockdown or pharmacological inhibition of LDHA suppressed cancer stemness, as determined by tumorsphere assay and decreased CD24/44 expression." (PMID 32839493, 2020). "For example, c-myc, a master regulator of transcription frequently overexpressed in cancer, increases the expression of lactate dehydrogenase A (LDHA), an enzyme which catalyzes the conversion of pyruvate into lactate." (PMID 32193527, 2020). "For instance, LDHA reduction resulted in an inhibited cancer cell proliferation, elevated cellular oxidative stress, and induction of apoptosis via the mitochondrial pathway." (PMID 32823815, 2020). "We found that the mRNA level of LDHA was significantly higher in cancer tissues than in adjacent normal tissues." (PMID 32859246, 2020). "Cancer cell migration and invasion increased due to LDHA elevation of the altered metabolic axis driven by activated CK2." (PMID 30926903, 2019). "LDHA is upregulated in multiple types of cancers and promotes metabolic reprogramming and malignant proliferation of cancer cells." (PMID 31523182, 2019). "Higher levels of both cleaved procaspase-3, procaspase-7 and cleaved PARP, are also observed in LDHA-defective cancer cells." (PMID 31035592, 2019). "We also found that increased LDHA in the modified metabolic pathway axis, driven by CK2α, regulates cancer cell migration and invasion." (PMID 30926903, 2019). "Consistent to the study, in this study we show that another LDHA inhibitor, MA, successfully suppressed their own growth of cancer cells." (PMID 31324019, 2019). "Among the 4 coding genes, LDHA was widely reported to promote malignant progress and predict poor survival in various cancer types." (PMID 31015800, 2019). "In a drug screen that targeted LDHA, we identified vitamin C as an agent capable of reversing the chronic stress–induced cancer stem-like phenotype." (PMID 30688660, 2019). "As such, both lactate and LDHA can be considered as promising molecular targets for the development of glycolytic inhibitors for possible use in cancer therapy." (PMID 31159361, 2019). "Based on these findings, lactate dehydrogenase A plays a crucial role in normal aerobic glycolysis as the overexpression of LDHA has been reported in highly glycolytic human cancers." (PMID 30886157, 2019). "In cancer cells, LDHA helps in rapid conversion of pyruvate to lactate, minimizing pyruvate entry into TCA cycle in the mitochondria." (PMID 31146503, 2019). "Lactate generated by CAF glycolysis is excreted by MCT-4, re-absorbed via cancer cell MCT-1 and converted back to pyruvate by cancer cell LDHA to then be oxidized in the TCA cycle." (PMID 31198853, 2019).
cancer (continued). "Results of comprehensive experiments conducted both in vitro and in vivo, LDHA exerted a cancer-promoting effect on the progression of OSCC by regulating cell glycolysis." (PMID 31921691, 2019). "Taking together, compound 11 is a new potent LDHA inhibitor, demonstrated by its ability to induce the reprogramming of MG-63 cancer cells metabolism from glycolysis to mitochondrial respiration decreasing cell survival." (PMID 31737570, 2019). "In hypoxia condition, observed in many types of cancer cells, LDHA is transcriptionally upregulated by the transcriptional factors responsible for the hypoxic adaptation such as HIF I and c-MYC8." (PMID 30886157, 2019). "The BxPc-3, MIA PaCa-2, PK-45P, and PK-1 cell lines had a stable and relatively high expression of PKM2 and LDHA at both stages of cell culture in comparison to the other cancer cell lines analyzed." (PMID 31527446, 2019). "Further, RASSF1A overexpression augmented HIF-1α promoter occupancy and transactivation of PDK1, HK2 and LDHA in both smooth muscle cells and cancer cells." (PMID 31086178, 2019). "Inhibitors of LDHA showed anti-cancer effect in different pre-clinical models, although clinical trials are halted due to low permeability or non-specific toxicity." (PMID 31638999, 2019). "For example, LDHA inhibitor quinolone 3-sulfonamides can reverse aerobic glycolysis in cancer cells." (PMID 31523182, 2019). "High levels of LDHA helps cancer cells to establish and proliferate by promoting epithelial to mesenchymal transition, angiogenesis, cytoskeletal remodeling, increasing cell motility, invasion and migration." (PMID 31146503, 2019). "In glycolytic cancer cells, a large amount of intracellular lactate was catalysed from pyruvate by lactate dehydrogenase A (LDHA)." (PMID 30443978, 2019). "LDHA partners with Rcl and acts synergistically to induce anchorage-independent growth establishing a role of LDHA in cancer progression." (PMID 31146503, 2019). "Similar to most aggressive cancers, LDHa was overexpressed in endocrine type cancers such as follicular thyroid carcinoma and papillary thyroid carcinomas compared to non-cancerous tissues." (PMID 31849832, 2019). "Taking advantage of multiple databases for human cancers and a novel aggregator called CANCERTOOL32, it is clear that LDHA expression is increased in a variety of human cancers." (PMID 30626875, 2019). "For development of novel anti-cancer drugs that effectively inhibit LDHA activity, we performed molecular modeling of the binding interaction between human recombinant LDHA and selected inhibitor ligands." (PMID 30850682, 2019). "Lactate dehydrogenase A (LDHA) is an important enzyme responsible for cancer growth and energy metabolism in various cancers via the aerobic glycolytic pathway." (PMID 31324019, 2019). "Even though increasing evidences have shown that the critical glycolytic enzymes, including HK2, PKM2 and LDHA, play important roles in cancer development, the drugs against these enzymes are far from clinical application." (PMID 31431517, 2019). "Reprogrammed glucose metabolism is one of the hallmarks of cancer, and increased expression of key glycolytic enzymes, such as pyruvate kinase M2 (PKM2) and lactate dehydrogenase A (LDHA), has been associated with poor prognosis in various malignancies." (PMID 31527446, 2019). "LDHA is aberrantly elevated in many types of cancers and acts as a key checkpoint of aerobic glycolysis in cancer cells." (PMID 31523182, 2019). "Studies have found that LDHA was upregulated in kinds of malignant tumors and can play an oncogene role in GC." (PMID 31637133, 2019). "Several previous studies demonstrated that pharmacological inhibition of LDHA activity or genetic knockdown of LDHA expression led to apoptotic cell death of cancer cells." (PMID 30850682, 2019). "As molecular regulation of LDHA and LDHB in different cancer remains obscure, we also review signaling pathways regulating LDHA and LDHB expression." (PMID 31146503, 2019).
cancer (continued). "The importance of the pHi/pHe gradient in cancer cells is emphasized by the blockade of LDHA resulting in decreased tumourogenesis." (PMID 31198853, 2019). "It has also been found that in glucose deprived conditions, c-Myc-transformed fibroblasts and cancer cells undergo extensive apoptosis through a unique glucose-dependent apoptotic pathway involving LDHA." (PMID 31146503, 2019). "One mechanism of action of LDHA inhibitors is to limit lactate export from cancer cells into the extracellular space." (PMID 31921661, 2019). "Twist, a representative EMT-inducing transcription factor is upregulated in invasive cancer cells and strengthened the glycolytic metabolic pathway by inducing LDHA expression." (PMID 31027222, 2019). "Collectively, the high expression of PKM2 and LDHA maintained the low intracellular levels of pyruvate in cancer cells." (PMID 30866966, 2019). "The high expression of LDHA following these metabolic alterations increased the migration and invasion of cancer cells." (PMID 30926903, 2019). "In cancer cells LDHA is tyrosine phosphorylated and was found to be phosphorylated at all four tyrosine sites by fibroblast growth factor receptor 1 (FGFR1)." (PMID 31146503, 2019). "Consistently, we demonstrate that chronic stress increases epinephrine levels to promote tumorigenesis and cancer stem-like traits via activation of the LDHA/USP28/MYC/SLUG signaling axis in a mouse model." (PMID 30688660, 2019). "Because replacement of endogenous LDHA with an acetylation mimetic mutant leads to a decrease of cancer cell proliferation and migration, LDHA acetylation plays a critical role in cell growth." (PMID 31035592, 2019). "We note that the expression of LDHA is up-regulated in the cancer tissues of all 14 cancer types examined except for LIHC." (PMID 31071451, 2019). "High glycolytic rates in drug-resistant cells are often accompanied with higher expression of glycolytic regulators such as PDK1 and LDHA, making these enzymes interesting targets for drug-resistant cancers." (PMID 30456204, 2018). "HIF-1α induces the over-expression of several glycolytic proteins including glucose transporters (i.e., GLUT1 and GLUT3), and enzymes such as hexokinase-1 (HK1), HK2 and LDHA in cancer cells." (PMID 30619850, 2018). "Our study provides a clue for how cancer cell balancing the demand of high proliferation rate and the high production of ROS: LDHA acts as a sensor for overloaded ROS, and then produce α-HB in the nucleus to enhance antioxidant capacity." (PMID 30356100, 2018). "Compatibility with high-throughput screening was highlighted by profiling a cancer-focused library and kinase inhibitor library for binders of LDHA and CDK9, respectively." (PMID 29930256, 2018). "Our study discovered a ROS-dependent manner of LDHA nuclear translocation in response to HR-HPV infection, and α-HB produced by nuclear LDHA act as an important antioxidant metabolite facilitating cancer development." (PMID 30356100, 2018). "What we discussed gives a precise insight into LDHA especially in cancer research, which will contribute to exploring cancer pathogenesis and its handling measures." (PMID 30403008, 2018). "Unlimited proliferation and resisted cell death are both hallmarks of cancer, and LDHA contributes greatly to cancer proliferation and survival." (PMID 30403008, 2018). "In many cancers, LDHA has a high expression profile and activated status, attributed to diverse mechanisms involving almost every step of gene expression regulation." (PMID 30403008, 2018). "C-Myc, which is overexpressed in Group 3 MB and activated downstream of Wnt signalling pathways, is also known to promote glycolysis in many cancers and upregulates LDHA expression." (PMID 29601482, 2018). "Inhibition of LDHA is gaining clinical prominence as a therapeutic intervention for diseases such as cancer and aging." (PMID 29795645, 2018).
cancer (continued). "Lactate dehydrogenase A (LDHA), the enzyme that converts pyruvate to lactate, is overexpressed in cancer, since the shift to oxidation of glucose to lactate is a well-known characteristic of the Warburg effect." (PMID 29805774, 2018). "LDHA is considered as critical for cancer cells since it catalyzes the conversion of pyruvate to lactate." (PMID 30024920, 2018). "The abundant expression of LDHA and lactate in the MB cell lines suggests they, like most cancers, have a glycolytic phenotype." (PMID 29601482, 2018). "Although the data presented here, and by others, using oxamate and LDHA to target cancer are promising, unfortunately the concentration of oxamate required to have significant effects is far too high to be considered for clinical use." (PMID 29601482, 2018). "LDHA, which is essential for the conversion of pyruvate into lactate, is preferentially expressed in cancer cells and is correlated with poor survival." (PMID 28915924, 2017). "The LDHA isoform is predominantly expressed in cancer cells and has higher affinity for pyruvate, favouring the conversion of pyruvate to lactate." (PMID 29615570, 2017). "Tyrosine kinase signaling can also target multiple nodes, including pyruvate dehydrogenase kinase and LDHA, and regulate aerobic glycolysis in cancer." (PMID 28598329, 2017). "More recently, Li and coworkers reported that Cetuximab reverses the Warburg effect in cancer cells via inhibiting HIF-1-regulated lactate dehydrogenase A." (PMID 28756482, 2017). "It has been found that LDHA gene expression is up-regulated in many human malignant tumors, such as cancers of the esophagus, stomach, lung, colorectum, and more recently, pancreas." (PMID 28056913, 2017). "MD-231 CM significantly increased the production of CCL5 in THP-1 macrophages; inhibition of LDHA greatly attenuated cancer cell-induced CCL5 secretion." (PMID 29299159, 2017). "A reduction in LDHA is also intriguing because increased LDHA is known to be a driver of glycolysis and subsequently cancer progression, a characteristic previously attributed to Lin28 over expression." (PMID 27230676, 2016). "Y10 phosphorylation of LDHA, which is common in many human cancers, promotes active, tetrameric LDHA formation, whereas phosphorylation of Y83 promotes NADH substrate binding." (PMID 26269128, 2016). "PKM2 and LDHA are two crucial glycolytic enzymes that facilitate these processes to confer cancer cells with a growth advantage over normal cells." (PMID 26989901, 2016). "The aim of our study was to evaluate the expression of PKM2 and LDHA in pancreatic pre-neoplastic lesions (cysts and pancreatic intraepithelial neoplasia, PanIN) and cancers and to correlate it with patient outcome." (PMID 26989901, 2016). "Several lines of evidence indicate that elevated levels of LDHA correlate with a higher grade of aerobic glycolysis and with poor prognosis in cancers." (PMID 27708237, 2016). "Some N-hydroxyindole-based LDHA inhibitors show an effective anti-proliferative activity in a series of cancer cells." (PMID 26918353, 2016). "LDHA is clearly more than just a metabolic gene that is overexpressed in cancer and the true extent of its function and the exact mechanism in which it operates in non‐neoplastic and neoplastic cells is only just beginning to come to light." (PMID 26269128, 2016). "Myc and HIF1A are the best-known transcriptional regulators controlling expression of glycolysis genes, such as GLUT1, HK2, PDK1, and LDHA, whose expression levels are highly elevated in cancer cells." (PMID 26989077, 2016). "In highly proliferating cells and cancer cells, LDHA is a key enzyme in the glycolytic cascade that converts pyruvate to lactate and cycles NADH back to NAD+ to sustain rapid proliferation." (PMID 27150057, 2016). "The critical role of LDHA in aerobic glycolysis has been proven in cancer cells, and LDHA depletion greatly decreases aerobic glycolysis and increases mitochondrial OXPHOS activity." (PMID 27282387, 2016).